NFE2L2 (NFE2 like bZIP transcription factor 2)
Diseases named in the same sentence as NFE2L2 in open-access papers (continued):
Sharing a sentence is not in itself a finding about the gene and the disease.
tumor (continued). "Two genes, MAFG and FECH were significantly upregulated in five and four tumour types, respectively, in the presence of NFE2L2 aberrations (FDR<0.1)." (PMID 26436532, 2015). "We conducted a meta-analysis of microarray data for 240 NFE2L2-mediated genes that were enriched in tumor tissues." (PMID 26596768, 2015). "A recent study suggested that the NFE2L2-mediated adaptation to oxidative stress is crucial for the early stages of tumour development." (PMID 23724128, 2013). "In these factors, like Interferon Regulatory Factor 1 (IRF1) and Nuclear factor, erythroid 2 like 2 (NFE2L2) have been reported to function in the anti-tumor capacity, while HIF-1 alpha (HIF1A) and Signal transducer and activator of transcription 3 (STAT3) to support tumor growth and immune evasion." (PMID 40230843, 2025). "The prolonged retention of IR808-ATIPA in tumor cells may overcome the transient protection mediated by NFE2L2 by extending oxidative stress exposure." (PMID 40831788, 2025). "Additionally, ATAC peak profiles for target genes in patient recurrent tumor samples, showed proximal gene linkages in clusters mediating the progenitor_photoreceptor signature and cycling progenitors for regulators such as NFE2L2, HLX, HSPH1, and KDM4B." (PMID 39711559, 2024). "What’s more, the TUNEL staining results showed that NSUN2 could significantly decrease the apoptotic levels of xenograft tumor tissues; silencing NFE2L2 substantiality reversed this effect." (PMID 38403250, 2024). "Molecularly, all tumor models exhibit common driver mutations in CTNNB1 and AXIN1, with TLCT models showing the characteristic TERT mutation, and some models progression-associated alterations in the NFE2L2 and NRAS genes." (PMID 39529166, 2024). "NFE2L2 is a master regulator of oxidative stress signaling and has dual roles in tumor progression." (PMID 38130953, 2023). "Interestingly, there was a significant association between the frequency of NFE2L2 MU and median TMB across multiple tumor types (r = 0.63, P < 0.001)." (PMID 37794491, 2023). "As a result, despite NFE2L2 MUs may be associated with a cold immune environment, immunotherapy may still produce therapeutic benefits and prolong survival for tumor patients with NFE2L2 MUs." (PMID 37794491, 2023). "For the metastatic Detroit 562 cell line, the least supportive CAFs were those derived from the CL mRNA subtype of HNSCC tumour mass characteristic by αSMA-low, elevated levels of oxidative stress response genes, including NFE2L2 and SOX2, and a history of heavy smoking." (PMID 35565415, 2022). "We further studied the relative expression of core cuprotosis risk genes NFE2L2, NLRP3, SLC31A1, and GCSH in GC STAD and confirmed that NFE2L2 has low expression in STAD tumor tissue, while SLC31A1 and GCSH genes were highly expressed in STAD tumor tissue." (PMID 36249422, 2022). "NFE2L2 is one of the main regulatory genes controlling significant cytoprotective effects on oxidative stress through the Nrf2–anti-oxidant response element (ARE) pathway and it is associated with tumor cell survival and treatment resistance." (PMID 35806488, 2022). "Additionally, whole-exome sequencing, in the context of tumor cells extracted from the surgically resected specimen, revealed that CTNNB1 and NFE2L2 mutations were the significant oncogenic mutations." (PMID 35382169, 2022). "The present study demonstrated that the KEAP1/NFE2L2/CUL3 mutations might be correlated to the lower immune infiltration and higher tumor mutation burden." (PMID 34617407, 2021). "The progression‐free survival (PFS) analysis, which can better reflect tumor progression and predict clinical benefits, also showed an association between KEAP1/NFE2L2/CUL3 mutation and faster disease progression (median survival time: 17.7 months vs. 31.7 months, p = 0.016)." (PMID 34617407, 2021). "Inhibition of NFE2L2 in keratinocytes favors tumor development." (PMID 34446793, 2021).
tumor (continued). "A study on the genome of ESCC used data from two clinical centers and found that NFE2L2 may be a tumor suppressor in ESCC." (PMID 33859939, 2021). "Mutations in NFE2L2, that specifically cluster to regions of the gene encoding amino acids in NRF2 that bind KEAP1, have been documented in early preneoplastic liver lesions and HCC tumour samples." (PMID 33276631, 2020). "Furthermore, we downloaded the data of tumor cell lines from the CCLE database and analyzed NFE2L2 expression in these tumor cell lines." (PMID 33101586, 2020). "Collectively, these results strongly suggest that NFE2L2 plays a vital role in tumor immunity." (PMID 33101586, 2020). "Until routinely applied anticancer drug combinations are available simultaneously targeting HGF, EGF and NFE2L2 mediated pathways, inhibition of overexpressed DYNLL, TNC, NCL and TMED2 may exert anti-tumor effect on HNSCC beyond their diagnostic role." (PMID 32564264, 2020). "Despite activating hotspots in NFE2L2 and inactivating mutations in its negative regulators, KEAP1, CUL3, and SIRT1 have been reported, they do not justify themselves the overexpression of NRF2 transcriptional signature in the different tumor types." (PMID 33233657, 2020). "Results showed that NFE2L2 was expressed in all 21 kinds of tumor cell lines." (PMID 33101586, 2020). "One important observation here is the reduced immune infiltrates in Redox tumors, which suggests that NFE2L2/KEAP1 signaling may lead to tumor evasion of immune surveillance programs." (PMID 31395880, 2019). "This supported the finding that PD-L1 expression in LUSC tumor cells was associated with NFE2L2 mutations and indicated that LUSC patients carrying NFE2L2 mutations may be more responsive to anti-PD-L1 immunotherapy." (PMID 29484121, 2018). "Notably, NFE2L2 TF activity was significantly higher in BAP1 mutant tumours than PBMR1 mutant tumours." (PMID 28139702, 2017). "Recent studies have shown that the context of NFE2L2 expression has a major influence on whether NFE2L2 exerts tumour suppressive or oncogenic functions." (PMID 27770790, 2016). "In addition, we observed generally lower NFE2L2 expression levels in tumour tissues than in normal breast tissues." (PMID 27770790, 2016). "In light of oestrogens acting as important ROS inducers ER positive tumours might accelerate their antioxidant response by upregulation of NFE2L2 activity to limit their exposure to oxidative stress." (PMID 27770790, 2016). "Furthermore, we compared NFE2L2 mRNA expression levels between tumour and normal breast tissue samples by means of 108 paired samples from the The Cancer Genome Atlas (TCGA) dataset." (PMID 27770790, 2016). "Notably, increased expression of several ROS hallmark genes involved in antioxidant response—Idh1, Nfe2l2 (NRF2), and Glrx—were validated by reverse transcription quantitative polymerase chain reaction (RT-qPCR) in both tumor-derived cell lines and whole tumor lysates." (PMID 40802750, 2025). "Thus, our model provides a mechanistic explanation for the clinical observation that KEAP1 mutant NSCLC tumours respond poorly to G12Ci drugs, and argues that alternative treatment strategies would be more appropriate for patients who present with KEAP1 or NFE2L2 mutant NSCLC tumours." (PMID 40890297, 2025). "Interestingly, in some patients, PIK3CA, KIT and NFE2L2 mutations are clonal in some tumor areas but absent in other ones, thus indicating a mixed and complex intratumoral clonal status." (PMID 36661697, 2023). "Different mechanisms can lead to aberrant sustained activation of NRF2 signalling in tumour cells, including somatic mutations in NFE2L2 or KEAP1, exon 2 skipping in NFE2L2, KEAP1 downregulation due to promoter hypermethylation, and transcriptional activation of NFE2L2 gene." (PMID 37373496, 2023). "However, tumor-suppressive effects of NFE2L2 have also been observed." (PMID 35059466, 2022). "In addition, we explored the correlation between NFE2L2 expression and tumor immunity." (PMID 33101586, 2020).
tumor (continued). "Notably, mutations in NFE2L2, KEAP1 and CUL3 that cause persistent upregulation of NRF2 often co-exist with mutations that activate KRAS and the PI3K-PKB/Akt pathway, suggesting NRF2 supports growth of tumours in which KRAS or PKB/Akt are hyperactive." (PMID 33276631, 2020). "However, we could observe significantly higher NFE2L2 mRNA expression levels in smaller tumours (T1) compared to larger ones (T2/3/4) (P = 0.045), and in progesterone receptor (PR) positive tumours (P = 0.040)." (PMID 27770790, 2016). "KEAP1 loss-of-function (LOF) and NFE2L2 gain-of-function (GOF) mutations exhibited a mutually exclusive pattern, demonstrating that the overexpression of NRF2 may contribute as pivotal mechanism in the selection of specific cancers or stages of tumor progression, including lung cancer." (PMID 40563292, 2025). "This highlights a potential role of the NFE2L2/MAFK axis in stress adaptation, drug resistance, and tumor progression." (PMID 40806565, 2025). "They utilized TIMER and the Tumor-Immune System Interactions Database (TISIDB) to analyze the correlation between NFE2L2 and CD163, focusing on co-expressed genes in tumor-infiltrating immune cells." (PMID 40191729, 2025). "Consistent with tumor suppression, effectors of tumorigenesis (Myc, Myb, NKX2-3, and TRIM24), metastasis (NFE2L2), oncogenic transformation (FOXM1), and cell cycle (E2F2 and E2F3) were also inhibited in the presence of PRKN." (PMID 39213189, 2024). "Nine CRGs were differentially expressed between tumor and normal tissues, among which NFE2L2, SLC31A1, FDX1, DLD, DLAT, and DLST were lowly expressed in tumor tissues, and ATP7B, CDKN2A, and GCSH were highly expressed in tumor tissues (p<0.05)." (PMID 37205181, 2023). "The expression of KEAP1, NFE2L2, and NOX4 were generally higher than normal level of body in more than 20 tumor tissue samples." (PMID 36627482, 2023). "High NFE2L2/NRF2 expression, however, increases tumor growth, metastasis, and resistance to anticancer therapy, as shown by recent research." (PMID 37946175, 2023). "Comparison of the TAL and RMC populations from the treated tumour revealed a transcriptional switch from high HOXB9 and TFCP2L1 activity in TAL1 cells, to high MYC, HIF1A, YY1 and NFE2L2 activity in RMC cells." (PMID 37236926, 2023). "Collectively, all results further strongly indicate that NFE2L2 and NOX4 play important roles in tumor immunity." (PMID 36627482, 2023). "In patient RNA sequencing data, SLC7A11, NQO1, NFE2L2 and GCLM gene expression was higher in CRUK0772 tumour regions compared to CRUK0640." (PMID 38168428, 2023). "NFE2 like bZIP transcription factor 2 (NRF2) is also a key molecule in ferroptosis, and in tumor cells, NRF2 prevents the accumulation of lipid peroxides and lipid oxidation of target proteins for survival purposes." (PMID 37152286, 2023). "CPTP was found to be involved in pyroptosis, and while its pro-tumor function in DLBCL was discovered in our study, HTRA1, RBBP7, NFE2L2 and SCAF11 were found to be tumor suppressive." (PMID 36551263, 2022). "NFE2L2 can increase MMP2 expression, which is an ECM remodeling marker and mediates tumor chemo-resistance." (PMID 35920986, 2022). "In tumor cell-enriched region, the expression of COPS5, DLAT, DLD, FDX1, NFE2L2, PDHA1 and PDHB in the high score group is higher than that in the low score group, while the opposite is true for DLST, GCSH and LIPT2 (P <0.05)." (PMID 36618352, 2022). "This analysis showed overexpression of the oncogenes VEGFA and NFE2L2, while KRAS was slightly reduced, in tumor samples of HNC." (PMID 35806488, 2022).
tumor (continued). "Interim analysis of DESTINY-Lung-01 study demonstrated 24.5% response rate using various genotypes such as P13K and CTNNB1, and also tumor suppressors STK11, KEAP1, and NFE2L2." (PMID 35978836, 2022). "NF-E2-related factor 2 (NFE2L2), another transcription factor with a bZip domain, supports tumor cell proliferation in part by activating oxidative stress response." (PMID 34339740, 2021). "Considering these findings, we could infer that tumor with KEAP1 or NFE2L2 mutation would have a higher level of oxidative stress, which could lead to the destruction of immune cells including CD8+ TILs and increased DNA damage level, resulting in the increase of somatic mutations of tumor cells." (PMID 31299995, 2019). "For example, constitutive activation of the transcription factor Nuclear factor erythroid-2–related factor 2 (NFE2L2, NRF2) in tumor cells up-regulates levels of the endogenous glutathione machinery, promoting tumorigenicity." (PMID 30459934, 2018). "Upstream, transcription factors such as NRF2 (NFE2L2) and ATF4 are known to upregulate SLC7A11 transcription, conversely, the tumor suppressor BAP1 represses SLC7A11 expression via H2A deubiquitination, thereby modulating cellular susceptibility to disulfidptosis." (PMID 41185600, 2025). "Moreover, other groups demonstrated a correlation between promoter methylation, histone acetylation status of NFE2L2/KEAP-1 and the biological function of several tumor cells." (PMID 38666930, 2024). "Among these genes, ATP7A and NFE2L2 did not display statistically significant differences in their expression levels between the tumor and normal samples." (PMID 38041690, 2024). "Mutations of Kelch-like ECH-associated protein 1 (KEAP1) or Nuclear factor erythroid 2-related factor 2 (NFE2L2/NRF2) lead to an activated KEAP1/NFE2L2 pathway in NSCLC, resulting in a discrete tumor phenotype with poor overall outcome and relative resistance to chemotherapy." (PMID 39528799, 2024). "Consequently, expression of NFE2L2, GPX4 and other anti-ferroptosis genes was upregulated in RMC cells from the MVAC-treated tumour compared to TAL cells, whereas many pro-ferroptosis genes were higher expressed in TAL cells." (PMID 37236926, 2023). "Once determined that T-ALL patients with high NFE2L2 levels exhibited increased NRF2 signalling, our next step was to investigate the molecular mechanisms activated in these tumours, which may contribute to tumorigenesis." (PMID 37373496, 2023). "Targeting NFE2L2 may represent an alternative strategy to increase efficacy of temozolomide (TMZ) and decrease the odds of tumor recurrence." (PMID 35920986, 2022). "Elevated levels of HIF1A, its target CAIX, and VEGFA transcripts are also seen in tumours with a gain of function or amplification of YB-1, although this was not the case for G3BP1 or NFE2L2 (encoding NRF2)." (PMID 34294889, 2022). "While tumor cells do not have high expression of NFE2L2 relative to myeloid cells, elevated expression occurs downstream of the Nrf2 pathway (NQO1, GPX2), which regulates oxidative damage repair." (PMID 35995947, 2022). "Identification of the possible roles of miR-17-5p and miR-612 in the regulation of NFE2L2 and VEGFA expression in PTC and colloid goiter can provide valuable insights for the development of strategies and drugs to inhibit tumor growth and also to restore sensitivity of tumors to chemotherapy." (PMID 32824922, 2020). "Tumor organoids and tumor tissue, but not normal tissue, from HB8 also both had a point mutation in NFE2L2, a gene involved in the regulation of oxidative stress." (PMID 32962010, 2020). "Unlike mutations in NFE2L2, somatic mutations in KEAP1 were found to be distributed throughout the gene, which represents the mutational pattern associated with tumour suppressor genes." (PMID 33276631, 2020). "We identified 13 variants that existed in cfDNA, but not in tumor DNA from comparison analysis, and three of these were located in driver genes (ARID1A, NFE2L2 and PIK3CA)." (PMID 31641155, 2019).
tumor (continued). "Furthermore, combining NFE2L2 inhibition with immunotherapies (e.g., CD19-targeted CAR T-cell therapeutics) could amplify tumor immunogenicity by increasing ROS accumulation and ferroptotic cell death, thereby boosting antitumor immune responses." (PMID 39534872, 2024). "Indeed in some cases of apparently non-cognate OG-tumor type combinations, there was selection in the copy-number gained state (NFE2L2 in CESC-POLE, U2AF1 in UC and other gene-tumor pairs with FDR ≤ 25%)." (PMID 39033140, 2024). "These investigations about immune infiltration and tumor environment indicated that the Wild group patients might have a higher immunotherapy response rate due to the TME status and the KEAP1/NFE2L2/CUL3 alterations that contribute to the tumor immune escape and “cold” tumor's formation." (PMID 34617407, 2021). "In addition to the tumor-derived cell lines, murine macrophages (RAW 264.7) responded fervently to PDT, inasmuch as these cells significantly upregulated all survival pathways (except for NFE2L2 in the LC90 group)." (PMID 27803950, 2017). "Interestingly, we did not observe DNA sequence mutations in the NFE2L2 or KEAP1 genes in OVCA, even though this mechanism of NRF2 activation is well established in many tumor types." (PMID 25114896, 2014). "Importantly, T-ALL patients with high NFE2L2 levels exhibited reduced overall survival, so one might speculate that drug resistance induced by increased GSH could be at least a contributing factor in these tumours." (PMID 37373496, 2023). "Moreover, mutant KRAS transcriptionally promotes metabolic reprogramming and upregulates Nrf2/NFE2L2, and it plays a critical role in anabolic cancer metabolism by altering glucose and glutamine metabolism KRAS enhances chemoresistance by upregulating Nrf2 signaling, critical for tumor progression." (PMID 35806488, 2022). "There was a negative correlation in the tumor tissue between miR-612 and VEGFA expression, and between miR-612 and miR-17-5p and NFE2L2 expression." (PMID 32824922, 2020). "Interestingly, we identified the prognostically relevant association between high NFE2L2 mRNA expression levels and better DSS and OS in the subgroup of patients with ER positive tumours (DSS: P = 0.013; OS: P = 0.004), but not in patients with ER negative tumours." (PMID 27770790, 2016). "However, we observed the downregulation of NQO1 in tumor tissue after SDT, which apparently did not match with the upregulation of NFE2L2." (PMID 34681196, 2021).